CGAS (cyclic GMP-AMP synthase)
Diseases named in the same sentence as CGAS in open-access papers (continued):
Sharing a sentence is not in itself a finding about the gene and the disease.
infection (continued). "Our previous study demonstrated that FHV-1 early infection could activate the DNA virus sensor, cyclic GMP-AMP synthase (cGAS), to induce the IFN-β." (PMID 31861450, 2019). "In addition, the anti-dsDNA antibody coimmunoprecipitated with cGAS, DDX41, and TFAM in cGAS-293FT cells after infection with WT PR8 influenza virus." (PMID 31604929, 2019). "Then again, we cannot rule out an involvement of IFI16 in sensing the dual infection and the cooperation of this sensor with cGAS in the activation of the antiviral IFN-β responses since block of IFI16 decreased the IFN-β response." (PMID 31867020, 2019). "The cGAS-STING pathway mediates IFN-I production in vitro in mouse cDCs, macrophages and fibroblasts, and in human embryonic kidney 293 cells after infection with the OPVs VACV or MVA." (PMID 31877196, 2019). "Infection levels in the CD11cCre-DDX41/cGAS siRNA group were not statistically different from those in the cGas KO/DDX41 siRNA group." (PMID 29871919, 2018). "Of note, given that pathogen infection increases host NTP levels, it is tempting to speculate that cGAS takes advantage of the higher intracellular NTP levels to increase its dimer population, potentiating its activation." (PMID 30295605, 2018). "In response to pathogen infection, cyclic GMP-AMP synthase (cGAS) binds cytoplasmic, pathogen-derived DNA to generate cyclic GMP-AMP (cGAMP), which binds to stimulator of interferon genes (STING), leading to co-recruitment of TBK1 and IRF3/7 promoting the activity of these transcription factors." (PMID 30223576, 2018). "In addition, the IFN-β luciferase promoter assay revealed that overexpression of cGas and Sting can induce IFN-β promoter activation following an ECTV infection." (PMID 29963044, 2018). "Considering the results obtained from a low dose of infection, we found slightly reduced expression of IFN-β, mild pathology, and higher viral loads in cGas−/− mice than in WT mice; therefore, a lethal dose of virus (1.0 × 106 PFU per mouse) was used for further animal infections." (PMID 29963044, 2018). "The SUMOylation- and ubiquitination-dependent dynamic regulation of cGAS stability ensures an efficient triggering of the cGAS-MITA pathway in the early phase of DNA virus infection, as well as its timely termination upon resolution of infection." (PMID 29546673, 2018). "While wild-type L929 cells markedly induced ISRE-IFNβ promoter-luciferase expression upon HSV-1ΔICP34.5 infection, TRIM56(+) cGAS(−), TRIM56(−) cGAS(+), or TRIM56(−) cGAS(−) L929 cells showed defective ISRE-IFNβ promoter-luciferase expression under the same conditions." (PMID 29426904, 2018). "Type I IFNs are induced downstream of cGAS and STING during infection with M. tuberculosis." (PMID 28529959, 2017). "Infection of macrophages with USA300 strain resulted in greater induction of Ifnb1 mRNA and IFN-β1 protein from mouse macrophages when compared to the DU5938 hemolysin-deleted strain, and this induction was similarly dependent on cGAS and STING." (PMID 28704551, 2017). "IFI16, H2B, BRCA1 and cGAS knockdown clearly demonstrate that a macromolecular complex of these molecules is necessary for STING activation and innate IFN-β response during KSHV and HSV-1 de novo infection." (PMID 27764250, 2016). "When WT, cGAS−/− and Stinggt/gt mice were challenged with HSV-1 (strains Mckrae or KOS), we observed severe disease development in mice with a defective cGAS–STING pathway, as shown by disease scores reflecting infection in both the eye and in the CNS." (PMID 27830700, 2016). "Neither BMMC activation nor IFNα production were affected by loss of SAMHD1, cGAS, or STING upon infection with Sendai virus (SeV), which is sensed via the RIG-I pathway." (PMID 27477283, 2016). "Meanwhile, siRNA depletion of cGAS inhibited detection of AdV+IgG 8 hours, but not 4 hours, post infection." (PMID 26506431, 2015).
infection (continued). "The role of these genes is not well understood although it is clear they inhibit HCV when expressed prior to infection, apparently at the level of translation and that they are also responsive to cGAS in the absence of a classical interferon response." (PMID 25912714, 2015). "Repeating our experiments using interferon priming to increase cGAS levels modestly beyond those under conditions of AdV+IgG or HRV+IgG infection at 4 hours post infection had no impact on sensing at either 4 hours or 8 hours." (PMID 26506431, 2015). "Moreover, infection with HSV1, a DNA virus known to activate cGAS, could also trigger GSDME-mediated pyroptosis in the presence of lactic acid or HCl." (PMID 40663398, 2025). "Importantly, the interaction between HDAC6 and TRIM56 was significantly upregulated at 4 h p.i., suggesting that HSV-1 early infection promotes the nuclear-to-cytoplasmic transport of HDAC6 and enhances its interaction with TRIM56, thereby reducing TRIM56-mediated cGAS-STING activation." (PMID 39747662, 2025). "Interestingly, treatment with the cGAS inhibitor G140 did not change the expression of viral receptors following infection." (PMID 41139159, 2025). "However, the documented activation of the cGAS-STING pathway in infected cells suggests that at least some viral capsids undergo disassembly in the cytoplasm, while others enter the nucleus in intact form to support productive infection." (PMID 41373786, 2025). "Cytosolic DNA sensing pathway of cyclic GMP-AMP synthase (cGAS) and stimulator of interferon genes (STING) is a major component of the antiviral response to DNA viruses, also known to play a relevant role in response to infection by RNA viruses, including foot-and-mouth disease virus (FMDV)." (PMID 38509419, 2024). "However, the cellular processes of protein degradation triggered by infection may also contribute to the decay observed for both cGAS and STING at late times after infection with high viral doses." (PMID 38509419, 2024). "In our experimental setup, PQBP1 did not seem to be involved in cGAS-mediated sensing, suggesting that its involvement could depend on the context of infection." (PMID 38530034, 2024). "Therefore, the cGAS-STING mechanism constitutes a comprehensive surveillance system in response to tissue damage and pathogen invasion, as abnormalities in this mechanism can result in infection." (PMID 38817608, 2024). "Thus, during infection with RNA viruses, the release of host genomic or mitochondrial DNA within the cytoplasm would not be detected and cGAS-STING-induced anti-viral immune responses will be inhibited." (PMID 39411713, 2024). "Altogether, our results indicate that the viral pMGF505-2R protein is involved in the modulation of the cGAS-STING signaling pathway and in the inhibition of IFN-β production, and consequently, the Arm/07-ΔMGF505-2R-GFP activates the innate immune response during infection." (PMID 38675789, 2024). "As a member of the PPR family, the cGAS protein acts as an innate nucleic acid sensor recognizing exogenous DNA generated by viral or bacterial infection or in the cytoplasm and converts ATP and GTP into 2’3’-cyclic GMP-AMP (cGAMP), which can be used to monitor pathogen infection or cellular stress." (PMID 39113033, 2024). "Similarly, whereas MVA infection of BMDCs triggered cGAS degradation, MVA∆E5R infection did not, confirming that E5 contributes to cGAS degradation in the context of either VACV or MVA infection." (PMID 37217469, 2023). "However, Mn2+-triggered anti-PRRSV XJ17-5 activity did not appear altered in cGAS-/- Marc-145 cells at both 24 h and 48 h post infection." (PMID 36992355, 2023). "Unlike WT VACV, VACV∆E5R infection of BMDCs did not result in cGAS degradation." (PMID 37217469, 2023).
infection (continued). "Furthermore, MVA∆E5R-E5-Flag infection of BMDCs resulted in much lower IFN-β production than MVA∆E5R, indicating that tagging of E5 with Flag at the C-terminus of the protein retained its inhibitory function on the cGAS/STING pathway." (PMID 37217469, 2023). "Finally, in addition to the direct synthesis of cGAMP by cGAS, STING signalling can be activated by cGAMP which is packaged into viral particles and exchanged between bystander cells in order to induce an antiviral environment and prevent infections." (PMID 37077526, 2023). "Moreover, MVA∆E5R infection failed to enhance E5-mediated cGAS degradation, indicating that E5 alone can trigger cGAS degradation, likely in the context of plasmid transfection." (PMID 37217469, 2023). "Since BAF contributed to cGAS degradation and was upregulated early in primary infection, we hypothesized that a BAF knockdown may also protect naive cells from subsequent primary infection with KSHV." (PMID 36746947, 2023). "Moreover, an infection of the Dengue virus and SARS-CoV-2 also causes the activation of the cGAS–STING pathway through cytosolic mtDNA rather than its genome." (PMID 37686127, 2023). "This makes it difficult to discern with certainty the extent to which mtDNA depletion might affect cGAS sensing as opposed to impairing apoptotic and inflammasome-driven responses, which as discussed later are common during infection with many RNA viruses." (PMID 38036506, 2023). "Notably, RNA viruses such as IAV and SARS-CoV-2 are thought to be recognized by RNA receptors such as Toll-like receptors and RIG-I rather than cGAS, a DNA receptor, upon infections." (PMID 37065192, 2023). "However, PRRSV and other RNA viruses do not form dsDNA or DNA : RNA complexes during infection, so cGAS must be activated by other means during the infection of these RNA viruses, but the mechanism is unclear." (PMID 35558078, 2022). "Interestingly, increasing evidences demonstrated that the cGAS-STING pathway, a key DNA sensor, restricted the infection of RNA virus, and the proteins of RNA virus could antagonize the cGAS-STING signalling." (PMID 36569928, 2022). "During wildtype MYXV infection, cGAS may not have access to MYXV genome DNA in the cytoplasm in order to induce IFN-I." (PMID 36103568, 2022). "Several mechanisms exist, directly or indirectly, to activate cGAS-STING–mediated immune response; the activation of this DNA sensing pathway generates cytokine and chemokines, which can change the cell’s internal environment and then help cells against the infection events." (PMID 36591232, 2022). "However, hepatocytes did not produce type 1 IFN upon foreign DNA stimulation or HBV infection, and mice lacking STING or cGAS show the same ability to control infection in an adenovirus-HBV model." (PMID 34386500, 2021). "We examined the mechanisms for cGAS activation in syncytial cells in the absence of infection, and hypothesized that cytoplasmic chromatin activates cGAS." (PMID 34732709, 2021). "Whether cGAS might rely on other intracellular cues that typify infection to increase the specificity of its activation is not known." (PMID 34111399, 2021). "At 12 h post infection, depletion of cGAS did not affect virus replication, while re-expression of cGAS in cGAS-null cells showed antiviral effects, possibly due to overexpression of cGAS." (PMID 34732709, 2021). "We found that loss of type I IFN production in cGAS and STING KO macrophages was not due to impaired bacterial engulfment or replication as bacterial burden was similar in control, STING KO and cGAS KO macrophages over the course of infection." (PMID 34473814, 2021). "In order to determine whether IFN signaling via the cGAS/STING pathway is generally employed by C. acnes to stimulate an IFN-I response independently of the phylotype, we performed infection experiments with C. acnes strain Asn12, the most potent IFN-I inducer, in cells lacking either cGAS or STING." (PMID 33178195, 2020).
infection (continued). "Components of the cGAS-STING pathway may be expressed at high levels in HSPCs, which may allow HSPCs to rapidly sense and respond to stresses, including infection and genotoxicity, by promoting HSPC proliferation, mobilization, and myeloid-biased differentiation." (PMID 33329537, 2020). "Our findings suggest that PPP6C-mediated dephosphorylation of a catalytic pocket serine residue of cGAS impairs its substrate binding activity and innate immune response, which provides a mechanism for keeping the DNA sensor cGAS inactive in the absence of infection to avoid autoimmune response." (PMID 32474700, 2020). "To date, although multiple enzymes and their corresponding PTMs have been identified to covalently modify cGAS or STING, little is known about how different PTMs crosstalk to each other and how the activities of enzymes that execute PTM are properly regulated during infection." (PMID 32532954, 2020). "Interestingly, no significant changes were detected in PKR or cGAS expression throughout infection in the newborn and adult brain besides a decrease in PKR levels at 24 h." (PMID 32457247, 2020). "Beyond cGAS/STING, using a murine model, the Oberst group has reported that the activation of ZBP1 and the downstream receptor interacting protein kinases 1 (RIPK1) and RIPK3 during infection is important in controlling ZIKV pathogenesis in the central nervous system (CNS)." (PMID 32899347, 2020). "cGAS is mainly known as a critical sensor for DNA viruses, and yet recent findings indicate that the cGAS-STING pathway might also be involved in responding to infection of positive-sense, single-stranded RNA viruses, including ZIKV." (PMID 31183075, 2019). "Together, these results highlight the importance of cGAS as the major cytosolic DNA sensor to ECTV and provide important insights into the innate mechanism that can curb viral dissemination from the initial site of infection, and its importance for overall virus control." (PMID 31877196, 2019). "Moreover, even though cGAS is expressed in human hepatocytes and is able to sense and signal upon transfection of naked relaxed-circular HBV DNA; during a natural infection, HBV DNA seems to escape cGAS detection, likely due to packaging of the genome into the viral capsid." (PMID 31426357, 2019). "Activation of STING was independent of the cytosolic double stranded DNA sensor cGAS, and infection did not induce detectable release into the cytosol of either mitochondrial, nuclear or bacterial DNA–indicating DNA-independent activation of the STING pathway in S. pyogenes infected macrophages." (PMID 29579113, 2018). "Whether the cGAS-dependent response is also required to control in vivo infection primarily in DCs is not known." (PMID 29871919, 2018). "By contrast, the role of cGas in the resistance to mousepox is not outstanding at the low dose of infection, but its importance was highlighted at the high dose of infection, which suggests that a weak or no role of cGas–Sting pathway is involved at a low dose of infection." (PMID 29963044, 2018). "To determine whether DDX41 and cGAS functioned in vivo to suppress infection, we subcutaneously inoculated the CD11cCre-DDX41 and cGas KO mice with MLV and measured infection levels in the draining lymph node; wild-type (Ddx41f/f mice without Cre) and Stinggt/gt mice served as controls." (PMID 29871919, 2018). "As cGAS seems to have both cytoplasmic and nuclear localizations, this begs the question whether nuclear populations of cGAS are involved in sensing HSV-1 and HCMV DNA during infection." (PMID 27935834, 2016). "moDC expressed similar amounts of cGAS compared with moMΦ (as shown by western blot and qPCR), and produced higher or similar levels of cGAMP compared with GM-CSF MΦ (as shown by mass spectrometry analysis) upon HCMV or MVA infection; however, moDC produced significantly less IFN-I than moMΦ." (PMID 27058035, 2016).
infection (continued). "During infection, viral nucleocapsids successfully target their cargo DNA to the nucleus, possibly activating either the canonical or noncanonical pathway, dependent on nuclear pools of cGAS or IFI16." (PMID 27935834, 2016). "Interestingly, we observed that the expression of cGAS, a recognized sensor for HIV-1 DNA in monocyte-derived DC, was more efficiently upregulated in cDCs from EC shortly after infection, but expression levels in alternative patients approached those of EC after 48 hours p.i.." (PMID 26067651, 2015). "Despite the similar baseline characteristics between WT and cGAS-/- mice, cGAS-/- macrophages demonstrate less prominent functions during stress and infection from the absence of cytosolic DNA signaling that might lead to an increase in some populations of bacteria." (PMID 41300373, 2025). "However, not all the canonical functions of cGAS are favorable for defensing infection." (PMID 38515746, 2024). "We speculated that the reason for this might be that a cytosolic DNA sensor, cGAS, competed in order for the substrate ATP to produce more cyclic-GMP-AMP (cGAMP), which binds to and activates the adaptor protein STING, resulting in IRF3 activation and IFNβ induction at the late stage of infection." (PMID 39205282, 2024). "This suggests that in spite of the presence of large quantity of viral genome DNA in the cytoplasm during ΔM062R infection cGAS still may not have full access to these DNA to generate large quantity of 2’3’-cGAMP probably due to the intact architecture of viral factories." (PMID 36103568, 2022). "The S. Typhimurium genomic DNA may also activate cGAS, supported by the observation that the transfection of S. Typhimurium DNA into macrophages can also provoke type I IFN response and bafilomycin A1 and chymostatin pretreated reduced type I IFN induction during infection." (PMID 35604097, 2022). "Interestingly, after infection of cells with MVA, cGAMP can diffuse through cellular gap junctions to activate the TI-IFN response in adjacent, uninfected cells, implying that the cGAS-STING system may directly stimulate bystander cells for resistance to incoming poxviral infection." (PMID 33092186, 2020). "Moreover, we also observed consistent phenomena in HSV-1-infected A549 cells with IFI16-/-, IFI16-/—STING knockdown or IFI16-/—cGAS knockdown, indicating that IFI204 might facilitate cGAS-STING DNA sensing pathway that leads to IRF3 activation during the infection of HSV-1." (PMID 31603949, 2019). "In reporter assays, mOPG147 and vOPG147 had no marked effects on ISRE activation induced by infection of Sendai virus (SeV), which is a RNA virus, suggesting that OPG147 specifically inhibits the cGAS-MITA pathway." (PMID 40498864, 2025). "HSV-1-and L. monocytogenes-infection induced S-nitrosylation of endogenous STING in PMs, but not cGAS, IRF3 or TBK1." (PMID 38409248, 2024). "And cytoplasmic Mn 2 + can induce cGAS activation and cGAMP production thus to initiate IFN-I responses in the absent of dsDNA without infection." (PMID 39183465, 2024). "Mn2+ was a potent cGAS activator and elicited the production of IFN-α, IFN-β, and other cytokines in the absence of infection." (PMID 38660494, 2024). "Interestingly, cGAS-STING–mediated protection against many intracellular pathogens including RNA viruses and S. enterica is hypothesized to be driven by the detection of mtDNA released into the cytoplasm upon infection, which emphasizes the potential for cGAS-STING activation by endogenous DNA." (PMID 37247757, 2023). "With the prolongation of infection, the reduced expression of STING was more obvious than control, whereas cGAS was not changed." (PMID 35871231, 2023). "On the other hand, knocking out cGAS, an endogenous mammalian cyclase upstream of STING, did not impair STINGPOX infection’s effects on IFN signaling." (PMID 36713447, 2022).